TRIM71 (tripartite motif containing 71)
Description:
E3 ubiquitin-protein ligase that cooperates with the microRNAs (miRNAs) machinery and promotes embryonic stem cells proliferation and maintenance (Probable). Binds to miRNAs and associates with AGO2, participating in post-transcriptional repression of transcripts such as CDKN1A (By similarity). In addition, participates in post-transcriptional mRNA repression in a miRNA independent mechanism. Facilitates the G1-S transition to promote rapid embryonic stem cell self-renewal by repressing CDKN1A expression. Required to maintain proliferation and prevent premature differentiation of neural progenitor cells during early neural development: positively regulates FGF signaling by controlling the stability of SHCBP1 (By similarity). Specific regulator of miRNA biogenesis. Binds to miRNA MIR29A hairpin and postranscriptionally modulates MIR29A levels, which indirectly regulates TET proteins expression.
Synonyms: LIN41; LIN-41; HYC4; HYDCC1
Tractability: Antibody: the Human Protein Atlas places it where antibodies can reach. PROTAC: UniProt records ubiquitination sites on it; ubiquitination databases record sites on it.
Gene: Protein-coding gene on chromosome 3 (32,817,526 to 32,897,824, forward strand). Ensembl gene ENSG00000206557.
Subcellular location: Cytoplasm, P-body
Subcellular location (Human Protein Atlas): Actin filaments; Focal adhesion sites; Plasma membrane
Pathways (Reactome):
Immune System: Antigen processing: Ubiquitination & Proteasome degradation
Gene Ontology:
Molecular function: miRNA binding; protein binding; translation repressor activity; ubiquitin protein ligase activity; ubiquitin-protein transferase activity; metal ion binding; zinc ion binding
Biological process: 3'-UTR-mediated mRNA destabilization; miRNA processing; negative regulation of translation; post-transcriptional regulation of gene expression; fibroblast growth factor receptor signaling pathway; G1/S transition of mitotic cell cycle; miRNA-mediated gene silencing by inhibition of translation; neural tube development; proteasome-mediated ubiquitin-dependent protein catabolic process; protein autoubiquitination; protein polyubiquitination; regulation of neural precursor cell proliferation; stem cell proliferation; protein ubiquitination; regulatory ncRNA-mediated gene silencing
Cellular component: P-body
Genetic constraint (gnomAD): Loss-of-function variants: 9 observed, 57.16 expected, observed/expected ratio (o/e) 0.16, 90% interval 0.094 to 0.28. The synonymous counts are far from expectation, so gnomAD's model fits this gene poorly and the ratio says little. Missense variants: 998 observed, 1,173.1 expected, observed/expected ratio (o/e) 0.85, 90% interval 0.81 to 0.9. Synonymous variants: 645 observed, 522.61 expected, observed/expected ratio (o/e) 1.23, 90% interval 1.16 to 1.32.
Homologues: Orthologues: chimpanzee TRIM71 (100% identical), macaque TRIM71 (99% identical), pig TRIM71 (98% identical), dog TRIM71 (97% identical), guinea pig TRIM71 (97% identical), mouse Trim71 (92% identical), rabbit TRIM71 (89% identical), tropical clawed frog trim71 (77% identical), zebrafish trim71 (72% identical). Paralogues in human: TRIM3 (29% identical), TRIM2 (28% identical), TRIM56 (17% identical), TRIM24 (16% identical), TRIM33 (16% identical), TRIM28 (13% identical), TRIM66 (12% identical), TRIM67 (12% identical), TRIM37 (12% identical), TRIM46 (12% identical), TRIM9 (12% identical), TRIM36 (10% identical), and 68 more.
Diseases named in the same sentence as TRIM71 in open-access papers:
TRIM71 is named in the same sentence as 38 diseases in open-access papers, as found by Europe PMC text mining. Sharing a sentence is not in itself a finding about the gene and the disease. The quoted sentences say what the papers report.
congenital hydrocephalus (7 papers, 2021 to 2026). Hydrocephalus that is present at birth. "Specifically, it has been found that mutations in TRIM71 are frequent in congenital hydrocephalus patients." (PMID 36590296, 2022). "Mutations in the RNA-binding domain of Trim71 can cause congenital hydrocephalus (CH)." (PMID 36757939, 2023). "Molecular studies on congenital hydrocephalus show that, exome sequencing of 125 CH trios and 52 additional probands identified 3 genes with significant burden of rare damaging de novo or transmitted mutations, in addition to TRIM71, there are SMARCC1 and PTCH1." (PMID 35356930, 2022).
hepatocellular carcinoma (6 papers, 2019 to 2024). A malignant tumor that arises from hepatocytes. "TRIM71 is up-regulated in hepatocellular carcinoma patients and is associated with tumor progression and poor prognosis." (PMID 33854615, 2021). "TRIM71 has been implicated in the growth and tumorigenicity of hepatocellular carcincoma, and LIN28B has been demonstrated to promote hepatocellular carcinoma cell progression as well." (PMID 38976670, 2024). "TRIM71 drove the carcinogenesis of hepatocellular carcinoma (HCC), and knockdown of TRIM71 significantly abolished liver cancer cell proliferation." (PMID 39267787, 2024). "In hepatocellular carcinoma cells, TRIM71 reduces p21 mRNA levels and promotes cancer cell proliferation." (PMID 36552825, 2022). "TRIM71 is upregulated in various cancer types, such as hepatocellular carcinoma, acute myeloid leukemia and ovarian cancer." (PMID 36552825, 2022). "TRIM71 was shown to promote proliferation in several hepatocellular carcinoma (HCC) cell lines as well as liver cancer progression in mouse xenograft models." (PMID 31732746, 2019). "For instance, TRIM71 has been correlated with advanced stages and poor prognosis in hepatocellular carcinoma." (PMID 31732746, 2019). "TRIM71 promoted proliferation of several hepatocellular carcinoma (HCC) cell lines presumably via ubiquitylation-mediated AGO1/2 protein destabilization." (PMID 31732746, 2019). "In order to gain molecular insight into the role of TRIM71 as an mRNA repressor, the present work focuses on the regulation of the known TRIM71 mRNA target CDKN1A, and its involvement in hepatocellular carcinoma cell proliferation." (PMID 31732746, 2019). "However, in line with later studies, we did not observe TRIM71-mediated changes in AGO2 stability in the cell lines tested, including the hepatocellular carcinoma line HepG2." (PMID 31732746, 2019).
embryonal carcinoma (5 papers, 2014 to 2023). A non-seminomatous malignant germ cell tumor characterized by the presence of large germ cells with abundant cytoplasm resembling epithelial cells, geographic necrosis, high mitotic activity, and pseudoglandular and pseudopapillary structures formation. "Additionally, we used the human GCT-derived non-seminoma cell line NCCIT to generate TRIM71 mutations via CRISPR/Cas9 in order to investigate the role of TRIM71 in the proliferation of pluripotent embryonal carcinoma cells." (PMID 34055789, 2021). "In a previous study, TRIM71 was shown to repress the mRNA of the cell cycle inhibitor and tumor suppressor CDKN1A/p21 in mES and embryonic carcinoma (EC) cells." (PMID 31732746, 2019).
Hydrocephalus (4 papers, 2019 to 2022). Hydrocephalus is an active distension of the ventricular system of the brain resulting from inadequate passage of CSF from its point of production within the cerebral ventricles to its point of absorption into the systemic circulation. "Detailed determinations in brain ventricles of Trim71 deficient mice suggest a biomechanical disruption due to deficient neurogenesis as the initial origin of hydrocephalus." (PMID 36590296, 2022). "Furthermore, two recurrent TRIM71 de novo mutations located in the NHL domain (R608H and R796H), which were also found to disrupt RNA binding, have been recently identified in a cohort of Congenital Hydrocephalus patients." (PMID 31732746, 2019). "Five genes (TRIM71, SMARCC1, PTEN, PIK3C, MTOR) were found to be involved in syndromic forms of hydrocephalus, and three other genes (FMN2, FOXJ1 and PTCH1) to be responsible for severe hydrocephalus with AS stenosis." (PMID 34092257, 2021).
liver cancer (4 papers, 2019 to 2025). An epithelial or non-epithelial malignant neoplasm that arises from the liver. "Among them, TRIM71 was specifically expressed in liver cancers and was associated with poor outcomes." (PMID 39267787, 2024). "To elucidate the molecular mechanisms underlying the overexpression of TRIM71 in liver cancer cells, we analyzed potential regulators binding on TRIM71 promoter regions using ENCODE database, and unexpectedly discovered the potential binding of retinoid X receptor alpha (RXRA) factor and EP300." (PMID 39267787, 2024). "IHC experiments revealed that liver cancer tissues induced by TRIM71 + YAP5SA mainly exhibited HCC-like and mixed HCC-ICC features, likely due to the influence of the YAP gene." (PMID 39267787, 2024). "In summary, this data collectively indicates that TRIM71 is a key regulatory RNA-binding protein in the construction of oncofetal ecosystem of liver cancer." (PMID 39267787, 2024). "As TRIM71 is a potential and liver cancer-specific driver analyzed in our previous studies, we aimed to clarify its oncogenic function in liver cancer." (PMID 39267787, 2024). "The results revealed that TRIM71 overexpression significantly enhanced the spheres formation ability of liver cancer cells in vitro." (PMID 39267787, 2024). "As TRIM71 maintains stemness and proliferation in mouse embryonic stem cells and participates establishment of oncofetal ecosystem in liver cancer, we tried to explore the role of TRIM71 in stemness of liver cancer." (PMID 39267787, 2024). "We will further explore the therapeutic effect of the cocktail therapy including ATRA combined with A-485 in the treatment of liver cancer patients with high expression of TRIM71." (PMID 39267787, 2024). "Our findings not only expand our understanding of oncofetal characteristics and related possible regulators but also provide a potential therapeutic option for liver cancer patients with high TRIM71 expression." (PMID 39267787, 2024). "The results revealed that Psph knockdown significantly suppressed the ability of TRIM71 alone or in combination with YAP5SA to induce liver cancer formation." (PMID 39267787, 2024). "We further identified that TRIM71 controls liver cancer cell proliferation and drives hepatocarcinogenesis in vitro and in vivo, which strengthens the importance of TRIM71 in liver cancer initiation and progression." (PMID 39267787, 2024). "In this study, we demonstrate the existence of an oncofetal status in liver cancer and the importance of TRIM71 in liver cancer initiation and progression." (PMID 39267787, 2024). "We have identified TRIM71 as a potential regulator for the oncofetal ecosystem and a liver cancer-specific driver in manipulating cancer initiation and progression." (PMID 39267787, 2024). "Taken together, these results suggest that TRIM71 specifically drives liver cancer initiation and progression." (PMID 39267787, 2024). "We performed immunoprecipitation-mass spectrometry (IP-mass) to uncover the binding cofactors with TRIM71 in HuH-7 liver cancer cells." (PMID 39267787, 2024). "This new regulatory mechanism provides a fresh perspective and critical regulatory targets for understanding how TRIM71 remodels liver cancer metabolism." (PMID 39267787, 2024). "In summary, we have described the oncofetal characteristics of liver cancers and identified TRIM71 as a liver cancer-specific driver and biomarker." (PMID 39267787, 2024). "Among these oncofetal RBPs, we found that TRIM71 is a liver cancer-specific oncogene that drives the initiation and development of liver cancer." (PMID 39267787, 2024). "We also performed TRIM71 overexpression experiments in hiHep normal liver cells 30 and Li-7 liver cancer cells." (PMID 39267787, 2024). "Meanwhile, we overexpressed TRIM71 and assessed its in vitro spheres formation ability in the liver cancer cell line Li-7, which exhibits low expression of TRIM71." (PMID 39267787, 2024).
liver cancer (continued). "In this study, we have discovered for the first time that TRIM71, as an RNA-binding protein, remodels the serine/glycine metabolic pathway in liver cancer, thereby controlling its malignant progression." (PMID 39267787, 2024). "To determine whether TRIM71 is a driver for liver cancer initiation and progression, we established two mouse models by hydrodynamic tail vein injection to deliver vectors into liver cells to induce malignant transformation." (PMID 39267787, 2024). "Recent evidence has revealed that TRIM71 is involved in liver cancer progression." (PMID 39267787, 2024). "To further elucidate the dependency of TRIM71 on the glycine/serine metabolism pathway in promoting liver cancer initiation and progression, we conducted knockdown experiments targeting the Psph gene in the previously two established TRIM71 mice models using hydrodynamic tail vein injection." (PMID 39267787, 2024). "Targeting the inhibition of TRIM71 using retinoic acid combined with A-485 may offer potentially therapeutic strategies for liver cancer patients with high TRIM71 levels." (PMID 39267787, 2024). "In pT3-TRIM71 or TRIM71 + YAP5SA mouse models of liver cancer induced by TRIM71, we found that TRIM71 alone or in combination with YAP5SA significantly increased the oncofetal levels, further suggesting that TRIM71 is a key regulatory factor in maintaining the oncofetal landscape of liver cancer." (PMID 39267787, 2024). "In addition to the classic oncofetal gene of LIN28B, we also found a more specific RBP, TRIM71, which is one of the top enriched genes in oncofetal liver cancer cells." (PMID 39267787, 2024). "In light of this, we further explored the cancer dependency score for TRIM71 in all CCLE cancer cell lines and strikingly noticed that among 10 cell lines, the viability of which was most affected by TRIM71 knockdown, four cell lines were derived from liver cancer." (PMID 39267787, 2024). "Taken together, these findings suggest that ATRA combined with A-458 may serve as a potential therapeutic strategy for TRIM71 high-expressed liver cancer patients." (PMID 39267787, 2024). "Pan-cancer analysis was found that TRIM71 was high expressed in liver cancer and ovarian cancer." (PMID 39267787, 2024). "As ATRA and A-485 could both inhibit TRIM71 expression and glycine/serine metabolism pathway, we hypothesized ATRA combined with A-485 could attenuate liver cancer initiation and progression with TRIM71 high expression." (PMID 39267787, 2024). "Furthermore, we identified that all-trans-retinoic acid (ATRA) combined with e1A binding protein p300 (EP300) inhibitor A-485 repressed TRIM71, attenuated glycine/serine metabolism, and inhibited liver cancer cell proliferation with high TRIM71 levels." (PMID 39267787, 2024). "As TRIM71 is vital for maintaining the dedifferentiation of stem cells and regulate glycine/serine metabolism, we hypothesized the potential regulation of RXRA and EP300 on TRIM71 in liver cancers." (PMID 39267787, 2024). "Our study highlights the potential inhibition of ATRA to TRIM71 transcription in liver cancer." (PMID 39267787, 2024). "Targeted inhibition of TRIM71 decreased liver cancer cell viability with high TRIM71 expression, suggesting that TRIM71 may be a core therapeutic target for liver cancer treatment." (PMID 39267787, 2024). "However, we also noted that the liver cancer tissues induced by TRIM71 + YAP5SA exhibited characteristics of both HCC and mixed HCC-ICC features." (PMID 39267787, 2024). "Similarly, let-7 downregulates E3 ubiquitin ligase TRIM71 in liver cancer." (PMID 39943201, 2025).
liver cancer (continued). "Importantly, ATRA combined with A-485 could enhance the inhibition of liver cancer cell proliferation with high TRIM71." (PMID 39267787, 2024). "Furthermore, we identified that all-trans-retinoic acid (ATRA) and e1A binding protein p300 (EP300) inhibitor A-485 could repress TRIM71 expression, dampens glycine/serine/threonine metabolism, and inhibits liver cancer cell proliferation." (PMID 39267787, 2024). "However, the detailed roles and molecular functions of TRIM71 need to be clarified in liver cancer." (PMID 39267787, 2024). "Hence, TRIM71 may serve as a liver cancer-specific biomarker and RBP in regulating fetal-like phenotype and maintaining the survival advantage conferred by oncofetal reprogramming, which deserves further exploration." (PMID 39267787, 2024). "In tumors, TRIM71 stabilizes m6A-modified CEBPA mRNA dependent on IGF2BP1, and ultimately facilitates liver cancer progression." (PMID 39267787, 2024). "To further investigate the mRNA regulatory relationship between TRIM71 and CDKN1A in normal liver and liver cancer, we analyzed m6A-RIP seq of HuH-7 cells and found CDKN1A mRNA has no significant m6A modification." (PMID 39267787, 2024). "Based on our preclinical results, we suggest that ATRA combined with A-485 exert anti-tumor ability through repressing TRIM71/CEBPA expression and decrease serine/glycine metabolism in liver cancer." (PMID 39267787, 2024). "To test the anti-tumor function targeting liver cancer initiation, we constructed YAP5SA + TRIM71 mouse model and treated with ATRA combined with A-458." (PMID 39267787, 2024). "In our work, we performed IP-mass and co-IP assays and identified the protein complex formed by TRIM71 with IGF2BP1, which stabilized CEBPA mRNA levels through an m6A-dependent manner in liver cancers." (PMID 39267787, 2024). "TRIM71 binds to and stabilizes the mRNAs of CEBPA, remodels PSPH and PSAT1 transcription, enhances the serine/glycine metabolic pathway, and ultimately promotes liver cancer progression." (PMID 39267787, 2024). "TRIM71 activates the glycine/serine metabolism pathway by remodeling the transcription of PSPH and PSAT1, thereby controlling the oncofetal characteristics of liver cancer and tumor initiation and progression." (PMID 39267787, 2024). "TRIM71 forms a protein complex with IGF2BP1, enhances mRNA stability of CEBPA with m6A-dependent manner, remodels PSPH and PSAT1 transcription, strengthens serine/glycine metabolism, and ultimately promotes liver cancer progression." (PMID 39267787, 2024). "Cell-counting kit 8 (CCK-8) assay and colony formation assay showed that TRIM71 knockdown significantly inhibited liver cancer cell proliferation with high TRIM71 expression but not in HCCLM3 with low TRIM71 levels." (PMID 39267787, 2024). "Conversely, PSPH and PSAT1 mRNA levels and protein levels were dramatically upregulated in TRIM71 and YAP5SA + TRIM71 mice liver tumor tissues compared to the control group, and inhibition of TRIM71 or CEBPA decreased cellular serine and glycine levels in HuH-7 and Hep3B liver cancer cells." (PMID 39267787, 2024). "Mechanistically, TRIM71 formed a protein complex with IGF2BP1, bound to and stabilized the mRNA of CEBPA in an m6A-dependent manner, enhance the serine/glycine metabolic pathway, and ultimately promoted liver cancer progression." (PMID 39267787, 2024). "Interestingly, both ATRA and EP300 inhibitor A-485 could decrease TRIM71 and CEBPA expression and dampen glycine/serine metabolism, and ATRA could enhance anti-tumor ability of A-485 in liver cancer." (PMID 39267787, 2024). "To determine whether the NHL domain regulates CEBPA expression and mediates the oncogenic function of TRIM71, we first infected liver cancer Li-7 cells with a TRIM71 lentiviruses lacking the NHL domain." (PMID 39267787, 2024).